EGFR (epidermal growth factor receptor)
Diseases named in the same sentence as EGFR in open-access papers (continued):
Sharing a sentence is not in itself a finding about the gene and the disease.
tumor (continued). "Patients whose tumours co-expressed c-erbB-2 and c-erbB-3, as well as those whose tumours co-expressed EGFR, c-erbB-2 and c-erbB-4 showed an unfavourable outcome compared with other groups, while combined c-erbB-3 and c-erbB-4 expression was associated with a better outcome." (PMID 15480434, 2004). "Using the same primary tissue samples, increased levels of epidermal growth factor receptor (EGFR) expression were detected in only 32% of tumour tissues, suggesting hPGFS may have the potential to become a drug target or molecular marker for SCCHN." (PMID 14997212, 2004). "However, a retrospective analysis of over 200 studies in different tumour types concluded that EGFR expression was a weak prognostic factor for NSCLC." (PMID 15187994, 2004). "Recent work has shown that tumour cell lines expressing high levels of EGFR may undergo apoptosis, particularly following exposure to EGF." (PMID 15365565, 2004). "Research in breast and other epithelial cell lines has suggested that HER-2 overexpressing tumours may be more sensitive to EGFR inhibitors such as gefitinib." (PMID 15150574, 2004). "Serum EGFR ECD level could be a candidate tumour marker for diagnosis, EGFR-targeted therapies and prognosis of NSCLC." (PMID 15226769, 2004). "Tumour cell survival and repopulation following radiotherapy in epithelial tumors may be regulated by the activation and expression of EGFR and its ligands following radiation." (PMID 15150574, 2004). "In three consecutive open-label Phase I trials, 52 patients with advanced tumours expressing high levels of EGFR were administered cetuximab intravenously as a single infusion (5–100 mg m−2), weekly for 4 weeks (5–100 mg m−2) or weekly for 4 weeks (up to 400 mg m−2) combined with cisplatin." (PMID 14760365, 2004). "However, an inverse correlation between IC50 and EGFR levels in a range of tumour cell lines has been reported." (PMID 15083203, 2004). "HER1/EGFR and HER3 have previously been linked to poor prognosis and tumour aggressiveness." (PMID 15505620, 2004). "Elucidating the biological effects of EGFR/erbB2 targeted therapeutics will enable patient tumor profiling to identify likely responders and the determination of biologically effective doses that allows chronic administration of these agents in order to maximise efficacy." (PMID 15305194, 2004). "This might suggest that the BT4C tumour growth inhibition at least partly involves direct antiproliferative effects, possibly through EGFR inhibition." (PMID 15305185, 2004). "Due to its pivotal role in the growth factor-mediated tumour cell migration, the adaptor protein phospholipase C-γ1 (PLC-γ1) is an appropriate target to block ultimately the spreading of EGFR/c-erbB-2-positive tumour cells, thereby minimising metastasis formation." (PMID 14710234, 2004). "The sustained ERK activation may reflect a difference in the regulation of EGFR activity in the tumour cells vs normal breast epithelium." (PMID 15280923, 2004). "In addition, the expression of EGFR in tumours has been correlated with disease progression, poor survival, poor response to therapy and the development of resistance to cytotoxic agents." (PMID 14583782, 2003). "A high level of EGFR, but not of Her-2, was strongly associated with tumour aggressiveness and poor survival." (PMID 12915878, 2003). "Conventional (clear cell) tumours showed an expected upregulation of EGFR." (PMID 14520461, 2003). "A great variety of tumours show abnormal, enhanced and/or constitutive expression of EGFR." (PMID 14583782, 2003). "Moreover, EGFR (over-) expression has been correlated with disease stage, reduced survival, development of tumour metastases and tumour differentiation in various cancers." (PMID 14583782, 2003). "By contrast, no expression of the EGFR mutation, EGFRvIII, often observed in non-NE cancer types, was detected in the human NE tumour models used." (PMID 14583782, 2003).
tumor (continued). "In conclusion, the underexpression of LRIG1 and the increase in EGFR/LRIG1 ratios found in RCC compared to the kidney cortex indicate that LRIG1 might be a tumour suppressor that counteracts the tumour-promoting function of EGFR." (PMID 14520461, 2003). "Thus, EGFR-TK inhibition appears to be a promising novel approach for the treatment of NE tumour disease." (PMID 14583782, 2003). "This has also been suggested for NE gastrointestinal tumours in which self-produced transforming growth factor α (TGF-α) and insulin-like growth factor (IGF) may autostimulate or transactivate EGFR and thereby promote tumour cell growth." (PMID 14583782, 2003). "The inhibition of telomerase activity triggered by antisense-epidermal growth factor receptor treatment may reflect yet another mechanism of antisense-epidermal growth factor receptor approach in tumour suppression." (PMID 11953893, 2002). "Recently, it has been shown that ionising radiation stimulates EGFR activation and cellular proliferation and that anti-EGFR antibody approaches can improve tumour radiation response." (PMID 11953865, 2002). "In addition, an inverse correlation between EGFR expression and the radiation cure rates of syngeneic murine tumours of different tissue origin has been demonstrated in preclinical studies." (PMID 11953865, 2002). "The basis of the increased activity of ZD1839 when combined with fractionated radiotherapy in tumour xenografts may result from inhibition of EGFR-mediated accelerated re-population between fractions." (PMID 11953865, 2002). "Among a panel of human tumour cell lines, these authors found that the cell line expressing the lowest EGFR levels demonstrated the greatest radioresistance, and that the greatest growth inhibition was observed for the cell line with the highest EGFR content." (PMID 11875748, 2002). "However, none of the other variables, including tumour size, grade, histological type, Manchester score, axillary lymph node status, tumour oestrogen receptor, progesterone receptor, Ki 67 and epidermal growth factor receptor expression, correlated with ATase." (PMID 12087469, 2002). "Therefore, the monitoring of the nude mice injected with antisense-EGFR transfected cells was continued until tumour volumes reached ∼1000 mm3." (PMID 11953893, 2002). "The inhibition of telomerase activity triggered by antisense-EGFR treatment may reflect yet another mechanism of antisense-EGFR approach in tumour suppression." (PMID 11953893, 2002). "This view has evolved through studies correlating EGFR expression with disease progression in multiple tumour types and evidence that EGFR-inhibition can influence a diverse range of pathways, including those involved in proliferation, reduced apoptosis, angiogenesis and invasion." (PMID 11953865, 2002). "Since many tumour cells express both ErbB-2 and EGFR and these receptors synergise in cellular transformation, therapeutic reagents simultaneously binding to ErbB-2 and EGFR might offer advantages for tumour therapy." (PMID 8826849, 1996). "This antibody effectively blocks the binding of EGF, transforming growth factor (TGF)-alpha and HB-EGF to the EGFR, inhibits the growth in vitro of tumour cell lines which overexpress the EGFR and eradicates such tumours when grown as xenografts in athymic mice." (PMID 8546911, 1996). "Moreover, post-operative residual tumour showed an independent role in predicting chemotherapy response (P = 0.0007) and EGFR status showed a borderline significance (P = 0.052) in the multivariate analysis." (PMID 7640219, 1995). "Twenty-two per cent of the tumours were EGFR positive using this assay." (PMID 7779717, 1995).
tumor (continued). "No significant clinicopathological correlations could be established, although the mean values for EGFR increased with tumour size and advanced clinical stage." (PMID 8519664, 1995). "Only two of the tumours overexpressed EGFR when compared with normal tissue." (PMID 8080726, 1994). "Athymic mice bearing xenografts of human tumours that overexpress the receptor (EGFR) for EGF and TGF alpha have been used to evaluate the therapeutic potential of three new rat monoclonal antibodies (mAbs) directed against two distinct epitopes on the extracellular domain of the human EGFR." (PMID 7679281, 1993). "The binding characteristics of EGFr were similar in tumour and normal breast membranes." (PMID 8427782, 1993). "When tested for their effect on tumour cells the mAbs were found to inhibit the growth in vitro of a number of human tumours that overexpressed the EGFR (e.g. HN5, HN6, HN15, A431, MDA-MB 468) but they were without effect on tumour cell lines expressing low or undetectable amounts of the receptor." (PMID 8094290, 1993). "EGFR and c-erbB-2 protein appeared to have additive effects in reducing the likelihood of response, and none of eight patients with EGFR positive, c-erbB-2 positive tumours derived benefit from endocrine therapy." (PMID 1346366, 1992). "In 12.5% overexpression of EGFR (score 3) was noticed in some of the tumour cells." (PMID 1457340, 1992). "Epidermal growth factor receptor can be used as a biological marker in tumours." (PMID 1931614, 1991). "Strong staining was found in 15% of tumours for c-erbB-2 and in 31% for the EGFr." (PMID 1712624, 1991). "Taking as positive those samples which showed a 20% difference between total binding and non specific binding, the EGFR was present in 39.7% of samples ranging from 36.4% in those tumours which were classified as being mucinous to 47.7% in the undifferentiated group." (PMID 1931614, 1991). "Combining EGFR-targeted delivery with albumin-based nanocarriers thus offers a powerful dual strategy: the targeting ligand directs the carrier to EGFR-overexpressing tumor sites, while albumin ensures stability, biodegradability, and efficient intracellular transport." (PMID 41489768, 2026). "Current preclinical models for studying EGFR-mutant LUAD include patient-derived cell lines, organoids, and xenograft models, yet these human-derived models cannot form tumors in immunocompetent mice, limiting insights into how EGFR mutations affect tumor-immune interactions." (PMID 41356800, 2026). "In some tumor entities, it has been effective to target the molecular tumor phenotypes caused by 10 of the identified CPGs, if mutated, including HRR deficiency, high TMB, activation of the epidermal growth factor receptor (EGFR), and p16INK4A dysfunction/deficiency (preclinical evidence)." (PMID 41546701, 2026). "Their role in GMB progression is mostly beneficial: they may enhance tumor growth by activating EGFR or TLR4 signaling in tumor cells, they support immune evasion by forming physical barriers for cytotoxic T cells or NK cells and contribute to treatment resistance by activating survival pathways." (PMID 41208963, 2025). "GFP-tagged EGFR in combination with Myc-tagged WT-USP8, USP8-P681Q variant, and the USP8-S718P variant as well as empty vector were transiently transfected into corticotroph tumor cells followed by immunoprecipitation with anti-GFP antibody linked agarose beads." (PMID 40386408, 2025). "Mutations in the EGFR gene, such as the EGFRvIII variant, lead to constant receptor activation and downstream signaling through the phosphatidylinositol-3-kinase (PI3K)/mammalian target of rapamycin (mTOR) pathway, promoting tumor growth and therapy resistance." (PMID 40650170, 2025).
tumor (continued). "Interestingly, EGFR signaling can also induce extracellular matrix remodeling via PKCδ-activation which leads to enhanced collagen deposition around tumor cells, reducing T-cell entry into the tumor." (PMID 40809430, 2025). "EGFR pathway-related metabolic changes may also affect the tumor microenvironment." (PMID 40486879, 2025). "Generally speaking, the presented ML pipeline could be deployed for other classification tasks (e.g., classification of EGFR or ALK mutation instead of KRAS, or tumor phenotyping as originally envisioned for radiomics), and besides radiomic features, any tabular dataset could be used or added." (PMID 39860023, 2025). "Of the 18 positive NGS results, 10 (56%) were concordant with primary tumor molecular alterations, while discordant samples consisted of gain of HER2 amplification in 4 (22%) cases, loss of estrogen receptor (ER) expression in 3 (17%) cases, and loss of EGFR mutation in 1 (6%) case." (PMID 40149379, 2025). "We selected KRAS, EGFR, BRAF, and MET mutations for inclusion in the multivariable model because they are among the most commonly altered driver mutations in LUAD and are known to significantly influence tumor behavior, prognosis, and response to targeted therapies." (PMID 40507306, 2025). "Without alternative activating mutations that could bypass EGFR inhibition, panitumumab effectively suppresses tumor growth by preventing ligand-induced receptor activation." (PMID 40076838, 2025). "In recent years, a better understanding of how cancer can adapt to treatment and become insensitive has suggested that, instead of waiting for tumor relapse, therapies could be designed to anticipate and delay the onset of resistance, thus prolonging EGFR-TKI response." (PMID 40846697, 2025). "Moreover, alterations in the tumor microenvironment can also sustain EGFR pathway activation." (PMID 40003951, 2025). "Specifically, common driver mutations, such as EGFR and KRAS mutations, have been found to be predominantly clonal, while failure to identify a driver clone may indicate a tumor composed of multiple subclones of different mutational origins without a dominant driver clone." (PMID 41345846, 2025). "The differential interactome composition indicates a functional shift in EGFR signaling that may drive increased tumor cell adhesion (CD44, ITGB1, FN1), metabolic adaptation (GAPDH, ENO1) and stress response (HSPA4, HSP90AB1), consistent with mechanisms observed in therapy‐resistant CRC phenotypes." (PMID 41319168, 2025). "Based on the results observed using CLSM, to investigate whether Vpr peptides can induce the release of tumor antigens, we used the membrane antigen EGFR as a representative and evaluated the EGFR level in the cell culture supernatants of HT-29 tumor cells treated with Vpr peptides using an ELISA." (PMID 40733687, 2025). "Interestingly, we found that enhanced levels of certain tumor markers, specifically CA199 and ProGRP, could be potentially used as simple and practical clinical predictors of EGFR 19del and T790M mutation detection by dPCR liquid biopsy assay." (PMID 40510243, 2025). "Therefore, the aim of this study was to identify the involvement of EGFR- and TLR-4-associated signaling pathways in bile duct epithelial cells during liver fluke infection-associated neoplasia in patients and animal models, as well as in a cellular model of host–parasite interactions." (PMID 40732668, 2025).
tumor (continued). "In consistent with these in vitro results, GPX4 and FSP1 levels were sufficiently reduced after CAP treatment, elevated in mice tumor samples carrying EGFR(Y1068F) mutation, and non-distinguishable in the 'EGFR(Y1068F)+CAP' group as compared with the control (mice inoculated with SUM159PT cells)." (PMID 39781456, 2025). "However, it remains unclear whether synergism between EGFR/KRAS mutations and FLCN LOH accelerates tumor progression in the lung." (PMID 40630489, 2025). "Subcutaneous tumor experiments based on the Osimertinib-resistant HCC827-TS cell line revealed that the HSP90 inhibitor AUY922 demonstrated considerable efficacy against Osimertinib-resistant EGFR-mutant LUAD, with IFI6 knockdown showing even greater therapeutic potential in vivo." (PMID 40234395, 2025). "Conversely, one study reported opposing findings, suggesting that miR-184 may act as a tumour promoter by enhancing tolerance to epidermal growth factor receptor (EGFR)-targeted therapies, thereby facilitating tumour progression when such treatments are inhibited." (PMID 41379397, 2025). "Furthermore, targeted inhibition of DPP4 delayed tumor recurrence in combination with EGFR‐TKIs." (PMID 40479551, 2025). "However, EGFR expression is usually reduced in HPV-positive tumours." (PMID 40655928, 2025). "Therefore, targeted inhibition of DPP4 may delay resistance to EGFR‐TKIs and eradicate residual tumor cells." (PMID 40479551, 2025). "While our model provides a non-invasive method to predict EGFR mutation status at baseline, it is important to recognize that mutation status alone may not capture the full spectrum of tumor adaptability." (PMID 41357203, 2025). "Interestingly, 24% of the cases had EGFR staining, which was present in ≥50% of the tumour cells." (PMID 40227788, 2025). "Interestingly, tumours with exon 19 EGFR deletions exhibited lower TMB than the L858R subgroup." (PMID 40647497, 2025). "Furthermore, recent studies have disclosed that amlodipine also exhibits anti-tumor effects on breast and lung cancer by inhibiting cell proliferation, inducing cell cycle arrest and promoting apoptosis, through suppression of the EGFR-Akt/mTOR or Raf/MEK/ERK pathways, instead of CCB activity." (PMID 41145413, 2025). "Interestingly, the similarity in survival and mutation status between groups implies that the underlying tumor biology—including molecular drivers like EGFR or ALK—is not significantly impacted by FPMH in this cohort." (PMID 40805843, 2025). "Despite other studies showing that cancers with mutated EGFR treated with erlotinib leads to increased tumor killing by NK cells, our studies do not show a reliable increase in NK cell killing by erlotinib, especially when compared to the NK cell killing induced by cSNX1.3." (PMID 39521886, 2025). "Notably, EGFR, a type I receptor tyrosine kinase, and its ligands play a pivotal role in regulating multiple cellular pathways involved in cancer cell proliferation, survival, and metastasis, and in tumor angiogenesis." (PMID 40149345, 2025). "These exosomes carry a large number of tumor-related proteins, such as EGFR, HER2, PD-L1, MET and GPC1, which may be used as cancer-specific markers; ii) a high level of stability, making them suitable for long-term storage and the detection of clinical samples." (PMID 40612948, 2025). "Notably, the presence of an EGFR exon 19 deletion in this tumor raises questions about whether oncogenic pathways influence antigen exposure or epitope spreading." (PMID 41179602, 2025).